ALB (albumin)
Diseases named in the same sentence as ALB in open-access papers (continued):
Sharing a sentence is not in itself a finding about the gene and the disease.
diabetic nephropathy (continued). "Albumin excretion rate and albumin/creatine ratio increased between 6 and 10 weeks following treatment with streptozotocin indicating the onset of diabetic nephropathy." (PMID 27055155, 2016). "Regarding creatinine clearance and urinary albumin excretion as early signs of diabetic nephropathy, insulin implants were able to correct the functional abnormalities described in the STZ-rat model." (PMID 27253523, 2016). "SGLT2 inhibitors were reported to ameliorate diabetic nephropathy, such as by attenuating urinary albumin excretion." (PMID 26999015, 2016). "Meta-analyses examining the effect of fish-oil in CKD secondary to IgA nephropathy, diabetic nephropathy and/or systemic lupus erythematosus showed reduction in albumin excretion and a trend towards slowing rate of decline in GFR." (PMID 27756237, 2016). "Increased urinary albumin excretion rate is the earliest clinical manifestation of diabetic nephropathy." (PMID 27036319, 2016). "All interventions with imidapril suppressed urine albumin excretion in the diabetic nephropathy mice." (PMID 27088094, 2016). "Paricalcitol therapy did not affect plasma N-terminal probrain natriuretic peptide concentration in patients with type 1 diabetes and diabetic nephropathy; however, the urinary albumin excretion rate was significantly lowered." (PMID 26109389, 2015). "Eight weeks after bone marrow cell transplantation, renal morphologic changes and clinical parameters of diabetic nephropathy, including the urine albumin/creatinine ratio and glucose tolerance, were measured in vivo." (PMID 26340671, 2015). "Diabetic nephropathy can be detected by the measurement of urine albumin or serum creatinine, and both tests should be performed at minimum annually; those with abnormal levels should have repeat tests done sooner." (PMID 28702221, 2015). "The diabetic mice showed significant terminal urinary albumin excretion in keeping with diabetic nephropathy compared to control mice (P<0.01)." (PMID 26509887, 2015). "The earliest manifestation of diabetic kidney disease can be detected by the presence of microalbuminuria, a state known as incipient diabetic nephropathy, where there is presence of small amounts of albumin in the urine (30–300 mg/day)." (PMID 24936198, 2014). "Hyperglycemia leads to the destruction of the glomerular filtration barrier, leading to glomerular damage and resulting in urinary protein or albumin leakage, exacerbating the progression of diabetic nephropathy." (PMID 25495844, 2014). "Diabetic Nephropathy was marked by increase in the Serum creatinine, Blood urea nitrogen in blood and albumin urea in urine." (PMID 24398037, 2014). "Compared with L-type CCBs, T-type CCBs resulted in an obvious decline in the urinary albumin to creatinine ratio (mean difference = −55.38, 95% CI −86.67–−24.09, p = 0.0005) in hypertensive patients with diabetic nephropathy." (PMID 25330103, 2014). "Diagnosis of diabetic nephropathy is based on the estimation of urinary albumin or eGFR by the Cockroft-Gault or MDRD equation." (PMID 25298884, 2014). "Oxidative stress is associated with renal dysfunction in patients with renal failure, and plasma albumin is the target of massive oxidation in nephrotic syndrome and diabetic nephropathy." (PMID 25187963, 2014). "The findings confirm that the albumin molecular structure is closely related to its redox state, and is a key factor in the progression of diabetes nephropathy." (PMID 25187963, 2014). "Meanwhile, in diabetic subjects, FVC and FEV1 were lower in those with diabetic nephropathy compared to those with normal albumin excretion (P<0.05)." (PMID 23618325, 2013). "Urinary albumin and creatinine have been considered as defensive biomarkers for diagnosis of diabetic nephropathy." (PMID 23409091, 2013).
diabetic nephropathy (continued). "An increment in the urine albumin excretion in 24 h was significantly aggravated in diabetic nephropathy that is an important sign to indicate progressive damage to glomerular and tubular cells in diabetic kidney." (PMID 24223616, 2013). "The MDRD Study, consisted of non-diabetic kidney disease and the total urine protein in this population likely contains in addition to albumin, non-albumin proteins such as β-2 microglobulin, retinol binding protein, and other low-molecular weight proteins." (PMID 23803596, 2013). "Treatment with telmisartan significantly reduced not only the urinary albumin excretion which was usually seen as an early manifestation of diabetic nephropathy but also the activation of the Notch pathway." (PMID 22319521, 2012). "Urinary albumin excretion has been demonstrated to be a good clinical predictor of renal lesions in diabetic nephropathy." (PMID 21837246, 2012). "Combined with albumin, it increases the power to detect diabetic nephropathy in those patients already proteinuric." (PMID 22645683, 2012). "Tubular dysfunction of albumin endocytosis via megalin can explain the microalbuminuria in the early-stage diabetic nephropathy." (PMID 22685655, 2012). "It has been reported that repetitive intraperitoneal injection of NEFA-bond bovine serum albumin leads to functional and structural alterations in mouse kidney with characteristics similar to those of diabetic nephropathy." (PMID 22412919, 2012). "Early alterations in diabetic nephropathy include development of glomerular hyperfiltration and glomerular hypertrophy, followed by increased urinary albumin excretion and eventually leading to glomerular sclerosis." (PMID 22988451, 2012). "Stimulation of soluble guanylate cyclase by riociguat significantly reduced urinary albumin excretion, a very early biomarker of diabetic nephropathy, in diabetic eNOS knockout mice on top of ARB treatment." (PMID 22900035, 2012). "Our results consistently demonstrate independent association between low serum albumin levels and increased LVMI and decreased LVEF in patients with diabetic nephropathy." (PMID 21860616, 2012). "Reduction rates of urinary albumin and maintained podocyte numbers, with parallel improvements in oxidative damage and inflammation, are related to beneficial effects of exercise in diabetic kidney disease." (PMID 22899901, 2012). "In this study, characteristic changes in early diabetic nephropathy such as increased urinary albumin excretion and glomerular hypertrophy were observed in diabetic rats." (PMID 22988451, 2012). "Diabetic nephropathy, as indicated by albumin/creatinine ratios as well as expression of stress-induced genes, was completely reversed by 2 months maintenance on a ketogenic diet." (PMID 21533091, 2011). "One-hundred-five patients with T2D were examined: 49 with normoalbuminuria (N, U-albumin/creatinine < 2.5 mg/mmol), 35 with persistent microalbuminuria (MA, 2.5-25 mg/mmol) and 21 with persistent macroalbuminuria/diabetic nephropathy (DN, > 25 mg/mmol)." (PMID 21696606, 2011). "Remarkably, within 2 months, diabetic nephropathy was completely reversed as indicated by urinary albumin/creatinine ratios." (PMID 21533091, 2011). "Current clinical biomarkers used to diagnose diabetic kidney disease, urinary albumin excretion and glomerular filtration rate, are subject to considerable measurement variability, and are heterogeneous as to prognostic impact." (PMID 20975990, 2010). "An increased urinary albumin excretion due dysfunction of the glomerular barrier is an early sign of diabetic nephropathy." (PMID 19653885, 2009). "Diabetic nephropathy is the leading cause of CKD and ESRD, and urinary albumin was originally used as a biomarker for the detection of CKD in diabetic patients." (PMID 19860890, 2009). "Urinary albumin was used as a biomarker to detect early-stage diabetic nephropathy in type 1 and type 2 diabetes." (PMID 19860890, 2009).
diabetic nephropathy (continued). "Microalbuminuria, the dominant feature of diabetic nephropathy is defined as an albumin excretion rate of 20–300 mg/24 hrs." (PMID 17187674, 2006). "The increase in urine albumin was seen with diabetic nephropathy was significantly higher than the other group subjects." (PMID 17187674, 2006). "Serum oxidized albumin levels may be useful for the early diagnosis of diabetic kidney disease and predicting renal outcomes." (PMID 40003909, 2025). "In model 2, after excluding SMI from the independent variables (as it was clearly confounded with PhA), sex, age, diabetic nephropathy, peripheral neuropathy, hemoglobin, serum albumin, LDL cholesterol levels, and eGFR were significant explanatory variables for PhA." (PMID 40786473, 2025). "Determining albumin and creatinine may help screen for microalbuminuria, enabling intervention before diabetic nephropathy becomes severe." (PMID 39810396, 2025). "Therefore, the presence of albumin in the urine has been considered predictive of the subsequent development and clinical progression of diabetic nephropathy." (PMID 40003909, 2025). "Next, there is evidence that glycated albumin may directly stimulate glomerular PKC activity in diabetic nephropathy." (PMID 40926896, 2025). "Early detection of diabetic nephropathy (DN) remains challenging, as conventional markers such as urine albumin-to-creatinine ratio (UACR) and estimated glomerular filtration rate (eGFR) are influenced by non-renal factors and lack sensitivity for subclinical injury." (PMID 41303131, 2025). "Furthermore, in the context of diabetic kidney disease, extracellular vesicles from albumin-treated tubular epithelial cells were found to induce M1 polarization through miR-199a-5p, which targets Klotho—a critical modulator of inflammation." (PMID 40534860, 2025). "Furthermore, isoflavone supplementation reduced urinary albumin excretion, reduced the urinary albumin-to-creatinine ratio, and delayed the progression of diabetic nephropathy in a diabetic db/db mouse model." (PMID 40003909, 2025). "Similarly, in a rat model of diabetic nephropathy, LS reduced urinary albumin excretion and SCr levels." (PMID 40542040, 2025). "Moderately increased urinary albumin excretion may serve as an early marker of diabetic nephropathy, which aligns with the increase in BUN and creatinine levels observed in the present study." (PMID 40493627, 2025). "For the earlier detection of diabetic Nephropathy, Micro-albumin, GFR, and UACR were estimated." (PMID 39626591, 2024). "Additionally, it is worth noting that approximately 30% of patients with diabetic kidney disease exhibit normal urine albumin levels." (PMID 39125705, 2024). "Furthermore, urinary albumin excretion, a marker for diabetic nephropathy, was ameliorated after treatment with propolis in a dose-dependent manner." (PMID 38419887, 2024). "In addition, advanced glycosylation end products, such as renal N-(carboxymethyl) lysine, HbA1c, and glycosylated albumin, are also related to the development of diabetic nephropathy." (PMID 38398510, 2024). "A total of 120 patients with diabetic nephropathy who were treated in the nephrology department of Quzhou People’s Hospital from March 2023 to March 2024 were selected and divided into three groups according to the urinary albumin creatinine ratio (UACR)." (PMID 39512612, 2024). "Moreover, in rats with nephropathy, crocin blocks diabetic nephropathy as indicated by decreased albumin and enhanced creatinine clearance." (PMID 37724538, 2023). "The study revealed that high serum uric acid levels could be related to deteriorated kidney functions and increased albumin excretion in diabetic nephropathy patients." (PMID 37370958, 2023). "Although diet patterns did not display significant associations, urine albumin levels prove promising as indicators of early-stage diabetic nephropathy." (PMID 37868453, 2023).
diabetic nephropathy (continued). "This study investigates the prevalence of a low ABI in patients with advanced-stage diabetic kidney disease, which was defined as a urinary albumin-to-creatinine ratio (UACR) ≥300 mg/g and an estimated glomerular filtration rate (eGFR) between 15–60 mL/min/1.73 m2." (PMID 36632822, 2023). "China’s Guidelines for the Prevention and Treatment of Diabetic Nephropathy (2021 edition) propose that the ratio of urinary albumin to creatinine (UACR) or 24-h urinary albumin excretion rate (UAER), estimated glomerular filtration rate (eGFR) and renal biopsy can be used for the diagnosis of DKD." (PMID 38115082, 2023). "This decrease in glomerular urinary albumin levels in c-MafΔTAM mice on STZ(12w) TAM(8w) could indicate improvements in diabetic nephropathy." (PMID 36787192, 2023). "Thus, this review will focus on the “traditional” course of diabetic kidney disease in type 1 diabetes with elevated albumin excretion at its core." (PMID 38192517, 2023). "Inflammation index fibrinogen-to-albumin ratio (FAR) has been shown to predict complications of type 2 diabetes (diabetic kidney disease and diabetes-related arteriosclerosis), but its relationship with mild cognitive impairment (MCI) in type 2 diabetes (T2D) is undetermined." (PMID 37576498, 2023). "The current study’s findings validated the onset of diabetic nephropathy that was observed via an increase in serum urea, and creatinine levels, urine volume, urinary microalbumin, and albumin excretion and a decrease in urinary excretion of urea and creatinine." (PMID 38044936, 2023). "However, given that the vast majority of diabetic kidney disease begins with an increase in albumin excretion, we should be able to detect most diabetic nephropathy with our albuminuria screen." (PMID 36114586, 2022). "TGF-β is a major pro-fibrotic factor in diabetic nephropathy that could mediate an increase in glomerular permeability to proteins, including albumin." (PMID 35381015, 2022). "Ito further pointed out that increased urinary copper excretion in patients with advanced diabetic nephropathy may be due to the copper-albumin and ceruloplasmin-copper complexes through the impaired glomeruli." (PMID 36562035, 2022). "Therefore, measuring urinary albumin levels is critical for suppressing diabetic nephropathy progression." (PMID 35955470, 2022). "Patients who were evaluated as having barriers to self-care PD but still performed PD without an assistant were older and demonstrated higher prevalence of diabetic nephropathy and PD-related infection, lower education level, and lower serum albumin (p < 0.05)." (PMID 35930437, 2022). "In an exploratory analysis, we also studied interactions between IL-9, the albumin/creatinine ratio (ACR) and urinary cytokines linked to the progression of diabetic nephropathy: vascular endothelial growth factor (VEGF), interleukin-6 (IL-6) and tumor necrosis factor alpha (TNFα)." (PMID 35445345, 2022). "Therefore, the term Diabetic Kidney Disease (DKD) encompasses both classical DN, with albumin loss in the urine and renal function impairment, and a particular form of nephropathy, distinguished by the reduction in GFR without albuminuria." (PMID 36139066, 2022). "Whether these markers are superior to the ratio of albumin to creatinine in providing earlier diagnosis for diabetic nephropathy require further analysis including annual follow-ups and monitoring before diabetic nephropathy develops." (PMID 35148702, 2022). "Additionally, FAR is a predictor of diabetic kidney disease with better performance than fibrinogen and albumin alone." (PMID 36006242, 2022). "The renal pathology in our case showed linear deposition of IgG in capillary collaterals and immunofluorescence of C3 (−), C1q (−), Fib (−), ALB (−), κ(+), lambda (+++), which could exclude diabetic nephropathy, which manifests as albumin deposition." (PMID 36377710, 2022). "HDL and ALB were negatively correlated with the occurrence of diabetic nephropathy." (PMID 35898464, 2022).
diabetic nephropathy (continued). "For instance, it reduced urinary albumin excretion in diabetic kidney disease patients." (PMID 36204481, 2022). "Furthermore, the diabetic nephropathy group was subdivided into two groups according to their Albumin-to-creatinine ratio (ACR) and was compared with the healthy group." (PMID 35712247, 2022). "Diabetic nephropathy among study subjects was categorized based on urinary albumin values." (PMID 34993041, 2021). "Transferrin has a molecular weight comparable to albumin, whereas transferrinuria and microalbuminuria in a 24-h urine sample may comparably reflect early diabetic nephropathy." (PMID 34743740, 2021). "The miRNA was also found expressed in renal tubules, in which it induced fibrosis through downregulation of the phospholipid phosphatase three gene, and its expression was found to be controlled by albumin, triggering the recruitment of NF-kB to the miR-184 promoter in diabetic nephropathy." (PMID 34897278, 2021). "In South Africa, diabetic nephropathy is diagnosed clinically using a digital community analyser vantage instrument that measures the amount of albumin and creatinine, as well as the ratio of albumin to creatinine (A/C) in urine." (PMID 34956850, 2021). "Urinary albumin estimation is the gold standard for the diagnosis of diabetic nephropathy." (PMID 34993041, 2021). "The authors concluded that RSV could be effective as an adjunct to angiotensin receptor blockers (ARBs) to diminish urinary albumin excretion in subjects with diabetic nephropathy." (PMID 34684678, 2021). "Similarly, in a small sample of patients with diabetic nephropathy, treatment with an iron chelator reduced albumin levels over a 9-month period." (PMID 34300354, 2021). "Furthermore, in diabetic nephropathy alleles -162 A and -1074 G as well as the 54 LL genotype, all associated with the lower PON1 activity, contributed to significantly higher urinary albumin loss." (PMID 33670025, 2021). "At present, we should admit that the ability of tetranor-PGEM level to discriminate the stage of diabetic nephropathy was inferior to the present clinical marker such as urinary albumin and protein levels since the stages of diabetic nephropathy are determined on these markers." (PMID 34560080, 2021). "There were 1,296 patients diagnosed with diabetic peripheral neuropathy (DPN), 2,077 patients diagnosed with diabetic retinopathy (DR), 836 patients diagnosed with diabetic nephropathy (DN), and 380 patients with DN who showed abnormal urinary albumin-to-creatinine ratio (UACR)." (PMID 33381172, 2020). "Another study suggests that renal tubular injury may precede glomerular injury of diabetic nephropathy, which may be the reason for the excretion of several urinary biomarkers occurs earlier than albumin." (PMID 33241962, 2020). "In addition, a Japanese study reported that serum IL-18 was correlated with carotid intima-media thickness and urinary albumin excretion in diabetic nephropathy patients." (PMID 32487168, 2020). "In the present study, our results reveal that bFGF could be a promising drug for the treatment of diabetic nephropathy, as indicated by reductions in urinary albumin to creatinine ratio and renal fibrosis." (PMID 32153399, 2020). "Moreover, isoflavones supplementation lowered urinary albumin excretion and decreased the urine albumin-to-creatinine ratio, which delayed the progression of diabetic nephropathy in diabetic db/db mice." (PMID 33379327, 2020). "Importantly, the addition of finerenone in patients with diabetic nephropathy resulted in improvement in the urinary albumin-creatinine ratio." (PMID 31507534, 2019). "We conducted a systematic review and meta-analysis of existing literature to evaluate the different outcomes of microRNAs (miRNAs) in diabetic nephropathy (DN), including urinary albumin excretion rates, urinary albumin creatinine rates, glomerular filtration rate, HbAc1, and creatinine." (PMID 30984273, 2019).